APOE (apolipoprotein E)
Diseases named in the same sentence as APOE in open-access papers (continued):
Sharing a sentence is not in itself a finding about the gene and the disease.
atherosclerosis (continued). "In addition, a strongly positive correlations between CHOP expression and the progression of atherosclerosis in human coronary arteries and carotid lesions as well as ApoE-/- mice have been reported during the past few years." (PMID 30515102, 2018). "In fact, this new mode of cellular regulation by apoE could explain results of earlier reports that documented its capacity to suppress type I inflammation and promote atherosclerosis regression beyond reducing plasma lipid levels." (PMID 29789495, 2018). "For PA image-guided therapy of atherosclerosis, ApoE−/− mice (male, 6–8 weeks) on a high-fat diet were randomly distributed into seven groups (n = 16): (a) control group; (b) Laser group; (c) CuS group; (d) CuS + Laser group; (e) CuS-TRPV1 group; (f) CuS-TRPV1 + Laser group; (g) capsaicin group." (PMID 29335450, 2018). "In this context crossing the Lyn−/− or Fgr−/− knockout strains with the ApoE−/− model of atherosclerosis provide an ideal test of this hypothesis." (PMID 29974666, 2018). "Additionally, the results found that ginsenoside Rb1 increased autophagy flux to inhibit apoptosis via acceleration of autophagy by promoting transformation of LC3 from type I to type II in high-fat diet-induced atherosclerosis in ApoE-/- mice." (PMID 30413028, 2018). "First, RIF protected ApoE KO mice fed a proatherogenic diet from atherosclerosis development." (PMID 29191818, 2018). "Furthermore, immunization of ApoE−/− mice with a preparation of killed P. gingivalis prior to homologous live bacteria oral challenge protected mice from accelerated atherosclerosis." (PMID 29621153, 2018). "In ApoE−/− and NOX1−/− animals, a reduction in the atherosclerotic area and the macrophages within the plaque were observed, suggesting a crucial for NOX1-induced ROS formation in the pathogenic process of ApoE-mediated atherosclerosis." (PMID 30140678, 2018). "These pigs could serve as ideal large animal models for the elucidation of ApoE gene functions and translational studies of atherosclerosis." (PMID 30305304, 2018). "A classical animal model for atherosclerosis is the ApoE−/− mouse." (PMID 29208753, 2018). "However, atherosclerosis was also exacerbated in ApoE−/− mice kept on high-fat diet by single or 3 repeated Cpn infections." (PMID 29770337, 2018). "To investigate whether levels of active AEP would increase in BSSM treated ApoE-KO mice with severe atherosclerosis, we evaluated the expression of AEP and the alteration of tau N368 truncated by active-AEP." (PMID 30337867, 2018). "Genetic deficiency or the inhibition of type 2-neutral sphingomyelinase (nSMase2), a key enzyme in sphingolipid metabolism, has been shown to decrease atherosclerosis in ApoE knockout mice by reducing inflammatory responses due to a decrease in ceramide levels." (PMID 30227643, 2018). "Atherosclerosis was also reported to be induced in ApoE(−/−) mice by radiation." (PMID 30513990, 2018). "SR-B1, a receptor for high-density lipoprotein, is involved in the regulation of endothelial cells in response to shear stress, which contributes to AAA formation in some patients with atherosclerosis and some animal models such as Ang II-infused ApoE gene knockout mice." (PMID 29849906, 2018). "There is substantial evidence for RAGE as a mediator of vascular disease, and importantly, mice lacking RAGE have attenuated atherosclerosis in apolipoprotein E deficient mice." (PMID 30467547, 2018). "Importantly, ApoE−/− atherosclerosis mice had decreased expression of UCP1, PGC1α, PRDM16, Cidea, and RPS3A." (PMID 30131868, 2018).
atherosclerosis (continued). "Thus, ApoE knockout (KO) rodent models have been favored in atherosclerosis studies and have provided valuable insights into mechanisms underlying this disease." (PMID 30305304, 2018). "More than 40 years after its discovery, apoE remains actively studied owing to its remarkable number of emerging pleiotropic properties, many of which contribute to the suppression of inflammation and atherosclerosis." (PMID 29789495, 2018). "One study found that miR-26a might exert an anti-apoptotic effect in endothelium by inhibiting TRPC6-induced calcium overload, and its expression was reduced in ApoE−/− mice with atherosclerosis induced by high-fat diet." (PMID 30285853, 2018). "However, another study reported increased lesion size in early stages of atherosclerosis in ApoE and ALX/FPR2 double-knock-out mice." (PMID 30487747, 2018). "The previous studies in rodents showing beneficial effects of inulin on hyperlipidemia and atherosclerosis were performed in LDL-receptor knockout mice and APOE-deficient mice, which are both models characterized by severely hampered lipoprotein remnant metabolism." (PMID 29401645, 2018). "In order to explore whether gut microbiota have any correlations with atherosclerosis in apoE KO mice, we performed a correlation analysis of family-level gut microbiota and aortic atherosclerosis lesion area." (PMID 30021609, 2018). "As atherosclerosis is accelerated both by hyperlipidemia and inflammation, we aim to determine the effect of dietary MOS on atherosclerosis development in hyperlipidemic ApoE*3‐Leiden.CETP (E3L.CETP) mice, a well‐established model for human‐like lipoprotein metabolism." (PMID 29665623, 2018). "These exciting new findings position apoE within the emerging field of intercellular communication that could introduce new approaches to control atherosclerosis cardiovascular disease." (PMID 29789495, 2018). "In addition, GPR119 expression is upregulated by oxidized low-density lipoprotein in THP-1 human monocyte cell line, and GPR119 overexpression inhibits the development of atherosclerosis in apoE-null mice." (PMID 30497501, 2018). "We studied levels of 8oxoG and its regulatory enzymes in human atherosclerosis, the mechanisms regulating 8oxoG repair and the base excision repair enzyme 8oxoG DNA glycosylase I (OGG1) in VSMCs in vitro, and the effects of reducing 8oxoG in VSMCs in atherosclerosis in ApoE−/− mice." (PMID 29643057, 2018). "TSLP has been shown to attenuate atherosclerosis in ApoE−/− mice." (PMID 28615347, 2017). "In addition, deletion of IL‐1β or the use of monoclonal antibodies against IL‐1β inhibited the development of atherosclerosis in apoE−/− mice." (PMID 28409825, 2017). "In this study, we aimed to evaluate the binding kinetics and pharmacokinetics of 15a for murine CCR2 (mCCR2) and determine whether this CCR2 antagonist is effective in an apoE−/− mouse model of atherosclerosis." (PMID 28246398, 2017). "In this study we first demonstrate that GTP could alleviate atherosclerosis via stimulating autophagy in high-fat diet (HFD)-fed ApoE-knockout mice." (PMID 28777810, 2017). "Also, low levels of apolipoprotein E (Apo E) have been related to hyperlipidemia and atherosclerosis." (PMID 28608804, 2017).
atherosclerosis (continued). "To investigate the role of TWEAK/Fn14 axis on diabetic-accelerated atherosclerosis, we studied the development of atherosclerotic plaques in Tnfsf12+/+ApoE−/−, Tnfsf12−/−ApoE−/−, and anti-TWEAK- or IgG-treated ApoE−/− in streptozotocin-induced diabetic ApoE deficient mice." (PMID 28447667, 2017). "Given that diabetic ApoE−/− mice have elevated cholesterol levels, one might argue that inhibition of atherosclerosis by CrP may be due to changes in the hyperlipidemic status of these animals." (PMID 28345659, 2017). "A mouse model with atherosclerosis induced by a high-fat diet (HFD) was built in ApoE (-/-) mice." (PMID 28536634, 2017). "Furthermore, apoE suppresses nuclear factor-κB mediated inflammation in monocytes and macrophages, thus supressing atherosclerosis." (PMID 28911329, 2017). "Although Ang-1 has been shown to have anti-inflammatory properties in endothelial cells, our present study clearly demonstrates pro-remodelling effects of Ang-1 on monocytes that translate into increased atherosclerosis in the context of elevated cholesterol levels in ApoE-/- mice." (PMID 28069704, 2017). "Periodontitis and atherosclerosis can be induced in apolipoprotein E knockout (ApoE−/−) mice." (PMID 29311898, 2017). "Moreover, in ATM+/− apoE−/− mice, atherosclerosis is attenuated by transplantation with ATM+/+ bone marrow." (PMID 28806901, 2017). "To assess whether this increased PAPP‐A expression was cause or consequence of lesion development, we studied apolipoprotein E (ApoE) KO mice, which are an established murine model of atherosclerosis." (PMID 28035757, 2017). "Here we show that SS-31 could ameliorate Western diet-induced deterioration of atherosclerosis in ApoE-/- mice." (PMID 28961281, 2017). "Immunization of ApoE(-/-) with different doses of the shortened peptide (Cramp) resulted in differential outcomes with a lower dose reducing atherosclerosis whereas a higher dose exacerbating the disease with increased neutrophil infiltration of the atherosclerotic plaques." (PMID 29091929, 2017). "We investigated the role of Ang-1 in atherosclerosis-prone apolipoprotein-E (Apo-E) knockout mouse." (PMID 28069704, 2017). "Importantly, treatment of ApoE-/- mice with an AT1 receptor antagonist inhibited progression of atherosclerosis." (PMID 28688452, 2017). "ApoE-deficient mice are characterized by high levels of oxLDL, and the APOE-ɛ4 allele is not just a risk factor for AD but also for atherosclerosis, a disease characterized by depletion of the specific subtype of IgM recognizing oxLDL." (PMID 28832675, 2017). "Conversely, low levels of ApoE expressed in adrenal cells can reduce the severity of atherosclerosis without affecting plasma lipid levels in ApoE-deficient mice." (PMID 28095860, 2017). "Our previous studies have found that TET2 inhibits atherosclerosis in ApoE knockout mice." (PMID 28798687, 2017). "For example, in ApoE deficient mice, combined treatment with ERK1/2 inhibitor and LXR ligand synergistically reduced atherosclerosis, which may function as a novel therapy." (PMID 28445156, 2017). "Decorin overexpression reduces atherosclerosis in ApoE KO mice." (PMID 28757161, 2017). "The key role of APOE in atherosclerosis has been reviewed previously." (PMID 28688452, 2017). "Therefore, we investigated the immunomodulatory properties of MSC in an acute and chronic model of lipopolysaccharide (LPS)-induced inflammation, emphysema and atherosclerosis development in APOE*3-Leiden (E3L) mice." (PMID 28910300, 2017). "Interestingly, VCAM1 expression–an inflammatory marker of endothelial cells involved in the development of atherosclerosis–and macrophage recruitment are both increased at the age of 9 weeks to similar levels seen in ApoE-/- mice." (PMID 28688452, 2017).
atherosclerosis (continued). "Hence, atherosclerosis in ApoE-/- mice advances in an age-dependent manner and lesion composition and progression is very much similar in humans." (PMID 28688452, 2017). "The potential immunogenic role of CRAMP in atherosclerosis in the context of MHC-I/self-peptide T cell reactivity was tested first in vitro by 24h or 48h stimulation of splenocytes harvested from 13 week old naïve ApoE(-/-) mice fed normal (NC) using tCRAMP." (PMID 29091929, 2017). "A longer follow up and the enlargement of patient number could provide a better understanding on the role of APOE in patients affected by advanced atherosclerosis." (PMID 28249002, 2017). "TLR3 activation has been found to promote atherogenic inflammation, especially in mediating plaque instability, while the absence of TLR9 exacerbates atherosclerosis in ApoE-deficient mice on a high-fat diet." (PMID 28769820, 2017). "In the present study, we evaluated whether EGFR-dependent pathways play a role in the development of atherosclerosis in ApoE−/− mice." (PMID 28374780, 2017). "ApoE KO mice are the rodent model most frequently used for studies of atherosclerosis." (PMID 28777298, 2017). "Taken together, our results reveal a specific glucocorticoid-induced increase in apoE gene expression in macrophages which may have therapeutic implications in atherosclerosis." (PMID 28355284, 2017). "Consequently, ApoE-/- mice provided the first practical model of hyperlipidemia and atherosclerosis." (PMID 29151984, 2017). "The purpose of this study is to clarify the influence of gut microbiota on the development of atherosclerotic lesion formation, systemic immune responses, and cholesterol and bile acid homeostasis using Conv and GF atherosclerosis-prone ApoE−/− mice fed a chow diet." (PMID 28130274, 2017). "ApoE knockout mice have increased oxidized lipids and develop atherosclerosis on high fat diet." (PMID 28344760, 2017). "The inexistent correlation between local and global PWV in ApoE-/- mice enforces the hypothesis of heterogeneously distributed initial effects of early atherosclerosis on the mechanical properties of the vessel wall." (PMID 28207773, 2017). "On the other hand, another report showed that DHA prevented chronic intermittent hypoxia-induced atherosclerosis but did not improve atherosclerosis in control apolipoprotein-E deficient mice." (PMID 28619112, 2017). "Also, housing mitoNEET-Tg mice at 16°C for 3-months significantly reduced the development of atherosclerosis when compared with ApoE knockout mice." (PMID 29311966, 2017). "ApoE knockout (ApoE-/-) mice as a model of atherosclerosis were used." (PMID 29151984, 2017). "In our study, a HFD resulted in lipid metabolic disorder and atherosclerosis in ApoE-knockout mice." (PMID 28777810, 2017). "However, despite its anti-oxidative and anti-inflammatory actions, Nrf2 knockout mice on an ApoE−/− background exhibited protection against atherosclerosis." (PMID 28253885, 2017). "Indeed, gugulipid increased aortic lesion size in atherogenic–diet-fed male ApoE KO mice, a well-established animal model of accelerated atherosclerosis." (PMID 28910310, 2017). "The present study showed that QSYQ attenuates atherosclerosis in ApoE-/- mice." (PMID 29137256, 2017). "Moreover, normalization of plasma lipids by transferring of ApoE+ bone marrow promoted the regression of atherosclerosis and led to the emigration of intra-plaque macrophages out of lesions." (PMID 28084332, 2017). "The present work demonstrated asperlin, a known polyketide isolated from marine Aspergillus versicolor LZD4403 fungus, as an effective agent that inhibited LPS-induced foam cell formation in RAW264.7 macrophages and prevented atherosclerosis development in ApoE−/− mice." (PMID 29135917, 2017). "APOE-knockout rabbits have recently been shown to generate hyperlipidemia with increased levels of cholesterol and triglycerides that mimic the symptoms of atherosclerosis in humans." (PMID 29099857, 2017).
atherosclerosis (continued). "Furthermore, GP-17 treatment substantially decreased lipid deposition and effectively stopped atherosclerosis formation in the ApoE−/− mice." (PMID 28208754, 2017). "The local increase of apoE gene expression in macrophages at the level of the atheromatous plaque may have therapeutic implications in atherosclerosis." (PMID 28355284, 2017). "Furthermore, the treatment of LV-let7g-sponge to apoE KO mice not only reduced let-7g levels in macrophages, but also increased both atherosclerosis and macrophage/foam cell apoptosis." (PMID 29254143, 2017). "Consistently, the IKKαf/f:MLysCre/apoE-/- mice had much milder atherosclerosis than apoE KO mice." (PMID 29254143, 2017). "Up-regulating CD36 expression promotes atherosclerosis in ApoE-/- mice." (PMID 28961281, 2017). "However, the presence of immuno-inflammatory responses to atherosclerosis are comparable between the human and ApoE(-/-) model." (PMID 29091929, 2017). "CD70 deficiency reduced spleen Treg in ApoE−/− mice and CD27 deficiency reduced Treg in solid tumor in mice, suggesting that CD27:CD70 may have an immunosuppressive role in atherosclerosis and tumor growth." (PMID 28738836, 2017). "In apolipoprotein E-deficient mice (a model of experimental atherosclerosis) galectin-3 is expressed in macrophage-rich areas, but not in smooth muscle cell-rich areas of aortic roots and brachiocephalic arteries." (PMID 28471381, 2017). "However, subsequent studies demonstrated that antibody-mediated depletion of pDCs inhibited experimental atherosclerosis in apolipoprotein-E (apoE)−/− mice." (PMID 28243244, 2017). "To investigate the potential role of immune auto-reactivity to hCAP-18 in atherosclerosis, we designed experiments with the Apolipoprotein E(-/-) [ApoE(-/-)] mouse model of atherosclerosis using the mouse homolog of hCAP-18, called CRAMP (Cathelicidin Related Antimicrobial Peptide)." (PMID 29091929, 2017). "In addition, we recently reported that SGLT2i suppresses the acceleration of atherosclerosis in diabetic apolipoprotein E-null (Apoe−/−) mice and macrophage foam cell formation in diabetic db/db mice in a glucose-dependent manner." (PMID 28408925, 2017). "Besides, NAC at 200 mg/kg was administered to ApoE -/- mice prevented the acceleration of atherosclerosis in this model." (PMID 28177049, 2017). "Another study on atherosclerosis was carried out in apolipoprotein E knockout (APOE-/-) mice." (PMID 28994736, 2017). "Furthermore, we observed that GF ApoE−/− mice have altered cholesterol and bile acid homeostasis, identifying gut microbiota as an effective therapeutic target for treating atherosclerosis and cardiovascular diseases." (PMID 28130274, 2017). "In ApoE−/− mice on pro-atherogenic diet, we observed Macroflor enrichment in the aortic root and arch, vascular territories that are affected by inflammatory atherosclerosis." (PMID 28091604, 2017). "Importantly, in this study, we utilized the diet-induced pig model of MetS-associated coronary atherosclerosis, which better represents the human setting than the mouse ApoE knock-out/cholesterol handling-dependent model of atherosclerosis." (PMID 28756533, 2017). "In the present study, we aimed to characterize immune cell infiltration in the vascular wall and perivascular tissue at early stages of spontaneous atherosclerosis development in apolipoprotein E (ApoE)−/− mice, and focused on possibilities for pharmacological modulation of this process." (PMID 27935022, 2017). "In addition, we utilized genetic knockout mouse models combined with apolipoprotein E (ApoE)-/- mouse to assess the effects of DKK3 on atherosclerosis, reendothelialization, and neointima formation after femoral artery injury." (PMID 28674110, 2017).